FAM9A (family with sequence similarity 9 member A)
Synonyms: TEX39A
Tractability: No criterion of Open Targets' tractability assessment is met for any kind of drug.
Gene: Protein-coding gene on chromosome X (8,790,795 to 8,801,383, reverse strand). Ensembl gene ENSG00000183304.
Subcellular location: Nucleus, nucleolus
Subcellular location (Human Protein Atlas): Mid piece
Gene Ontology:
Molecular function: protein binding
Biological process: meiotic cell cycle; spermatid development
Cellular component: synaptonemal complex; nucleolus
Homologues: Orthologues: chimpanzee FAM9A (75% identical), macaque FAM9A (52% identical), tropical clawed frog sycp3 (17% identical), zebrafish sycp3 (14% identical), rat Xlr5c (10% identical), mouse Xlr3a (10% identical), mouse Xlr3b (10% identical), mouse Xlr3c (10% identical), mouse Xlr5b (10% identical), mouse Xlr5c (10% identical), rat LOC100911047 (10% identical), mouse Xlr5a (10% identical), and 8 more. Paralogues in human: FAM9B (36% identical), FAM9C (30% identical), SYCP3 (18% identical).